RN7SKP213 (RN7SK pseudogene 213)
Gene: Miscellaneous RNA gene on chromosome 2 (219,590,687 to 219,590,984, reverse strand). Ensembl gene ENSG00000222678.
Homologues: Orthologues: chimpanzee 7SK (99% identical), guinea pig 7SK (61% identical). Paralogues in human: RN7SKP180 (77% identical), RN7SKP255 (76% identical), RN7SKP269 (76% identical), RN7SKP9 (76% identical), 7SK (75% identical), RN7SKP203 (75% identical), RN7SKP245 (75% identical), RN7SKP85 (75% identical), RN7SKP193 (74% identical), RN7SKP45 (74% identical), RN7SKP131 (74% identical), RN7SKP146 (74% identical), and 284 more.